CXCL8 (C-X-C motif chemokine ligand 8)
Diseases named in the same sentence as CXCL8 in open-access papers (continued):
Sharing a sentence is not in itself a finding about the gene and the disease.
ovarian carcinoma (continued). "Therefore, we conclude that the development of targeted molecules to inhibit CXCL1 and CXCL8 may be a promising strategy for suppressing ovarian cancer progression and achieving therapeutic benefits." (PMID 37762405, 2023). "Therefore, PGK1 may affect the recruitment of neutrophils by regulating the level of CXCL8, leading to the progression of ovarian cancer." (PMID 34277429, 2021). "Vorinostat has also been shown to induce the IL-8/CXCL8 expression in ovarian cancer cells, which is dependent on IκB kinase (IKK) activity and is associated with gene-specific recruitment of IKKβ and IKK-dependent recruitment of p65 NFκB to the IL-8/CXCL8 promoter." (PMID 31067680, 2019). "Elevated serum levels of the pro-inflammatory chemokine interleukin (IL)-8 (CXCL8) are associated with disease burden and poor prognosis in multiple tumor types, including melanoma, renal cell carcinoma, non-small cell lung cancer (NSCLC), pancreatic, breast, and ovarian cancer." (PMID 31091832, 2019). "In a cultured cell line derived from the ascites of a patient with platinum resistant ovarian cancer (ET2), elevated levels of CCL2, CCL3, CCL4, CCL5, CXCL1, CXCL8 and CXCL10 were detected in the cultured media." (PMID 41424784, 2025). "There were strong positive correlations between expression levels of CXCL8 and p-GSK-3β/p-p70S6K1, showing that p-GSK-3β and p-p70S6K1 levels were important in CXCL8 expression in ovarian cancer." (PMID 39660100, 2025). "At the same time, higher protein levels of CXCL8, p-GSK-3β (Ser9), and p-p70S6K (Thr389) were found in ovarian cancer tissues." (PMID 39660100, 2025). "For example, CXCL8 initiates the epithelial-mesenchymal transition (EMT) program and activates Wnt/beta-catenin signaling in ovarian cancer cells, promoting cancer cell invasion and metastasis." (PMID 37765018, 2023). "Although CXCL1 expression is found in a significant number of ovarian carcinoma cases, its role can be largely played by CXCL8/IL-8, whose expression is found in all cases of ovarian carcinomas." (PMID 37108425, 2023). "We found that exposing ovarian cancer cells to catecholamines induced the expression of CXCL1 and CXCL8 chemokines, which were shown to promote cancer cell progression in a dose-dependent manner." (PMID 37762405, 2023). "Our results align with these findings and show that CXCL1, CXCL5, CXCL8, and CXCL11 are overexpressed in ovarian cancer." (PMID 36969851, 2023). "The transcriptional levels of CXCL1, CXCL8, CXCL10, CXCL11, CXCL12, CXCL13, and CXCL14 were significantly elevated while CXCL3 was obviously reduced in ovarian cancer vs normal ovarian tissue." (PMID 33763130, 2021). "Our results showed that CXCL1, CXCL8, CXCL9, CXCL11, CXCL12, CXCL16, and CXCL17 were remarkably elevated in ovarian cancer compared to those in normal tissue." (PMID 33763130, 2021). "Pyruvate dehydrogenase kinase 1 (PDK1) promotes ovarian cancer cell angiogenesis, invasion, and metastasis through α5β1 integrin and JNK/CXCL8 signaling." (PMID 35011369, 2021). "The CXCL8/STAT3 pathway plays a key role in M2 macrophage polarization and stemness of ovarian cancer stem-like cells." (PMID 35011369, 2021). "Overexpression of GAB2 in ovarian cancer cells promotes tumour growth and angiogenesis by upregulating the expression of CXCL1, CXCL2 and CXCL8, which are IKKβ-dependent." (PMID 31895688, 2020). "It is very plausible that this effect was associated with the higher secretion levels of several agents known to support ovarian cancer cell progression by these cells, such as CCL2, CXCL8, CXCL12, ICAM-1, IL-6, HGF, PAI-1, uPA, TGF-β1, and VEGF." (PMID 31086083, 2019). "Induction of CXCL-8 expression and release by HDAC inhibition in ovarian cancer decreased their efficacy." (PMID 30841513, 2019). "In the case of ovarian cancer cells, their motility was fueled by CXCL1/GRO-1, CXCL8/IL-8, IL-6, TGF-β1, and fibronectin." (PMID 28956065, 2018).
ovarian carcinoma (continued). "They secrete IL-6, IL-8/CXCL8, CCL2, and adiponectin, which act on cancer cells via their respective receptors to support ovarian cancer cell metastasis." (PMID 28275576, 2017). "The top distinctive genes for the proliferation metaprofile include, besides previously used markers, numerous genes related to malignancy and ovarian cancer progression, in particular cytokines and their receptors: CXCL1, IL1A, CXCL8, IL1B, IL1R1, and IL1R2." (PMID 29362714, 2017). "We found that overexpression of GAB2 in ovarian cancer cells upregulated expression of multiple chemokines, including CXCL1, CXCL2 and CXCL8 that exhibited mitogenic and pro-angiogenic activities." (PMID 26657155, 2016). "Suppression of GAB2 in all three ovarian cancer cell lines decreased the mRNA levels of CXCL1, CXCL2 and CXCL8." (PMID 26657155, 2016). "In this report we show that senescent human peritoneal mesothelial cells (HPMCs) alter the secretory profile of ovarian cancer cells (A2780, OVCAR-3, SKOV-3) by increasing the release of four angiogenic agents: CXCL1, CXCL8, HGF, and VEGF." (PMID 26433963, 2016). "Overexpression of GAB2 upregulated the secretion of several chemokines from ovarian cancer cells, including CXCL1, CXCL2 and CXCL8." (PMID 26657155, 2016). "We showed that inhibition of IKKβ by both genetic and pharmacological means effectively reduced the transcription of CXCL1, CXCL2 and CXCL8 in GAB2-overexpressing FTSECs and ovarian cancer cells." (PMID 26657155, 2016). "Particularly, ovarian cancer cell lines express high levels of proinflammatory chemokines CXCL1-3 and CXCL8 as specific ligands for the chemokine receptor CXCR2." (PMID 27723802, 2016). "Taken together, these findings suggest that overexpression of GAB2 in ovarian cancer cells promotes tumor growth and angiogenesis by upregulating expression of CXCL1, CXCL2 and CXCL8 that is IKKβ-dependent." (PMID 26657155, 2016). "CXCL8/IL-8 is a prototype of the ELR+ CXC chemokines that promote angiogenesis, tumorigenesis, and metastasis in many human cancers, including ovarian cancer." (PMID 26414070, 2015). "One of the primary findings in this study is that in these four ovarian cancer cell lines, CCL20, CXCL1-3 and CXCL8 were the major chemokines that responded to EGF or TNF by involving NF-κB, Akt and Erk signaling pathways." (PMID 23800251, 2013). "Our results indicate that CCL20, CXCL1-3 and CXCL8 are the primary chemokines induced by EGF or TNF and are elicited in these ovarian cancer cells via NF-κB, Akt and Erk signaling pathways." (PMID 23800251, 2013). "Our results indicate that ovarian cancer cells induce CCL20, CXCL1-3 and CXCL8 as the primary chemokines in response to EGF or TNF." (PMID 23800251, 2013). "In our previous study, ovarian cancer cell lines highly expressed CXCL1-3 and CXCL8 which all have a high affinity for CXCR2." (PMID 24376747, 2013). "The chemokine network revealed that ovarian cancer cells commonly expressed high levels of proinflammatory chemokines such as CCL20, CXCL1-3 and CXCL8 in response to EGF or TNF." (PMID 23800251, 2013). "CXCL1 and CXCL8, in particular, have been identified as secreted proteins regulated by EGF and the PI3K pathway in ovarian cancer cell lines." (PMID 23800251, 2013). "A study showed that stroma-derived MMP1 activate protease-activated receptor-1 (PAR1) expressed in ovarian cancer cells, and the epithelial-stromal crosstalk induces the secretion of CXCL1 and CXCL8 from cancer cells." (PMID 24213462, 2012). "In the ovarian cancer cell line SKOV-3, CXCL8/IL-8 was shown to induce transient phosphorylation of EGFR and its association with the adaptor molecules Shc and Grb2, suggests an important cross-talk between chemokine and growth factor pathways." (PMID 20049170, 2010).
ovarian carcinoma (continued). "Other chemokines potentially involved in cancer progression include CCL18, which promoted ovarian cancer migration, CCL20, which promoted both metastasis and chemotherapy resistance, and CXCL8 (IL-8), which may contribute to peritoneal metastasis." (PMID 40689422, 2025). "Further, when CXCL8 binds to CXCR1/2, it can activate transforming growth factor beta-activated kinase 1/Nuclear factor-kappa B (TAK1/NFκB) signaling and enhance the migration and invasiveness of ovarian cancer cells." (PMID 37377954, 2023). "Also in ovarian cancer, CAF secrete other secretory factors, including VEGF, IL-6, granulocyte colony-stimulating factor (G-CSF), CCL2/MCP-1, and CXCL8/IL-8, which are involved in tumorigenesis and lead to cancerous tumor growth." (PMID 37108425, 2023). "Moreover, in ovarian cancer, stromal cells, surrounding the tumor, release CXCL1, CXCL2 and CXCL8 exerting a chemoprotective role on cancer cells and contributing to polarize monocyte/macrophage toward an M2 tumor promoting phenotype." (PMID 33066172, 2020). "In addition, hospicells synergized with ovarian cancer cells to secrete increased amounts of proangiogenic VEGF, IL-6, and CXCL8/IL-8." (PMID 28956065, 2018). "Moreover, several soluble factors of mesothelial origin have been found to stimulate other vital elements of ovarian cancer cell progression, including proliferation (CXCL8/IL-8, IL-6), migration (CXCL12/SDF-1, HA), and invasion (LPA)." (PMID 28956065, 2018). "Other research documented that ovarian cancer cells subjected to omental adipocytes display increased homing, migration, and invasion in mice, and that a potent role in this behavior was played by adipocyte-derived CXCL8/IL-8." (PMID 28956065, 2018). "In addition, KLF4 was identified as a putative upstream regulator of drug resistance in ovarian cancer and together with ST3GAL5, SYNE1, CXCL8, HERC5, FOSL1, ARRDC4 merits further studies." (PMID 28473707, 2017). "Our recent studies in endometrial and ovarian cancer suggested that CXCL1 and/or CXCL8 secreted by human cancer cells and signalling via their receptors CXCR1 and/or CXCR2 could be implicated in human ASC migration." (PMID 27241286, 2016). "Together, these findings suggest that overexpression of GAB2 in ovarian cancers may contribute to upregulation of CXCL1, CXCL2 and CXCL8 expression in a context specific manner." (PMID 26657155, 2016). "Based on the synergistic increase of CCL20 and CXCL8 in response to EGF and TNF, CCL20 and CXCL8 may be the dominant chemokines found in ovarian cancer cells with abundant TNF, and/or activation of the EGFR." (PMID 23800251, 2013). "Interestingly, saxatilin, a snake venom shown to inhibit TNF-induced proliferation in ovarian cancer cells, was found to block the TNF effect by suppressing CXCL8 expression." (PMID 24376747, 2013). "Although CXCL8 or CXCR1/2 siRNAs have not yet been used clinically, a pre-clinical orthotopic ovarian cancer model has illustrated anti-tumor effects upon silencing of CXCL8 gene expression using liposome-encapsulated siRNA." (PMID 24276377, 2013). "GAB2 can activate CXCL8 and induce the expression of zinc-finger E homeobox-binding-1 (ZEB1) through the activation of the PI3K signaling pathway, which directly inhibits the transcription of E-cadherin, further promoting the migration and invasion of ovarian cancer cells." (PMID 37377954, 2023). "In addition, class I HDACs but not class II HDACs regulate CXCL-8 expression in ovarian cancer." (PMID 30841513, 2019).
ovarian carcinoma (continued). "To examine whether high GAB2 levels in ovarian cancer cells are required for expression of CXCL1, CXCL2 and CXCL8, we suppressed GAB2 with inducible shRNAs in FUOV1 cells and observed that induced suppression of GAB2 decreased the mRNA levels of CXCL1, CXCL2 and CXCL8 compared with un-induced cells." (PMID 26657155, 2016). "Here, we show that in addition to ovarian cancer SKOV3, OVCAR3, and CAOV3 cells, HDAC inhibition induces the CXCL8 expression in HeLa cells, but not in CTCL Hut-78 cells." (PMID 29050320, 2017).
periodontitis (295 papers, 2008 to 2026). An acute or chronic inflammatory process that affects the tissues that surround and support the teeth. "Consistently, increasing concentrations of chemokines such as TNFα, IL1β and CXCL8 in the gingival crevicular fluid and peri-implant crevicular fluid are associated with the severity of periodontitis and peri-implantitis." (PMID 40565042, 2025). "We focused on CXCL-8 since this chemokine is associated with inflammatory tissue destruction in periodontitis and periodontal tissue homeostasis." (PMID 35187533, 2022). "IL6 and CXCL8/IL8 are central cytokines in the inflammatory response, and their dysregulation has been strongly implicated in the pathogenesis of periodontal diseases such as gingivitis and periodontitis." (PMID 39769290, 2024). "We detected a significant increase in mRNA levels of Interleukin (IL)-1β, IL-17 and the chemokines Cxcl1 and Cxcl2 which are important neutrophil chemoattractants (corresponding to Cxcl8 in humans) in gingival tissue derived from CD73-deficient animals with periodontitis when compared to the WT." (PMID 38152410, 2023). "Despite its importance in defense, the production of CXCL-8 in already inflamed tissues, such as in periodontitis, may contribute to the loss of the connective tissue and the destruction of the alveolar bone." (PMID 35602018, 2022). "Concurrently, host neutrophils in periodontitis lesions exhibit hyperactivation, secreting chemokines (e.g., CXCL8) and cytokines (e.g., TNF-α and IL-1β), which amplify monocyte recruitment and chronic inflammation." (PMID 41009952, 2025). "Of these, CXCL1 and CXCL8 were significantly upregulated after P. gingivalis infection and also upregulated in periodontitis epithelial cells from scRNA-seq data." (PMID 41358003, 2025). "In the process of periodontitis, chemokines such as CXCL-8, CXCL-1, and CCL-5 and cytokines such as TNF-α, IL-1β, and IL-6 are present, due to the action of these multi-factors, it progresses to severe periodontitis with loss of periodontal support structures." (PMID 40733170, 2025). "The CXCL8 SNP, particularly, rs2227307, appears to influence the clinical manifestations of periodontitis." (PMID 39201416, 2024). "By comparing differentially expressed genes in neutrophils between the two groups, several inflammation‐associated genes, such as IL1B, CD44, CXCL8, and CCL4 were upregulated in the gingivae from patients with periodontitis versus healthy subjects." (PMID 37639212, 2023). "On the other hand, it has been reported Curcumin molecule bind to CXCL8 chemokine and inhibit ferroptosis in ligature-induced periodontal-diseased mice, thus, play a pivotal role in treatment of periodontitis." (PMID 38033572, 2023). "TGFB1I1, VNN1, HLADRB4, and CXCL8 genes were differentially expressed in lymphocytes and monocytes of subjects with poorly controlled diabetes mellitus, dyslipidemia, and periodontitis in comparison with controls." (PMID 36233348, 2022). "CXCL-8 production by gingival epithelial cells is dependent on the composition of the microbial community, and data on CXCL-8 levels in the gingival crevicular fluid of periodontitis patients are still contradictory." (PMID 35602018, 2022). "Statistical analysis revealed that the CXCL8 level in PISF was significantly lower than in patients with moderate periodontitis (p = 0.011)." (PMID 33726736, 2021). "It was observed that the concentration of CXCL8 in each group of patients with periodontitis varied significantly according to the stage of the disease." (PMID 33726736, 2021). "In contrast, the level of CXCL8 in PISF was substantially lower than in patients with moderate periodontitis." (PMID 33726736, 2021). "TNF-α, CCL2, IL-6, IFN-γ, and CXCL8 showed significantly higher levels in GCF from periodontitis patients compared to control subjects (p < 0.05)." (PMID 34502071, 2021).
periodontitis (continued). "From an epigenetic point of view, CXCL8 was markedly hypomethylated in aggressive periodontitis patients, suggesting CXCL8 as a potential etiological factor in the pathogenesis of AgP." (PMID 32867386, 2020). "In persons with periodontitis, the levels of IL-8/CXCL8 in both periodontal tissue and GCF are drastically increased and have been correlated with disease severity." (PMID 24151615, 2013). "Interactions between HtpG and the TLR4 and CD91 receptors induce the chemokine CXCL8, a chemoattractant for phagocytic cells in periodontitis and thus perpetuating the uncontrolled inflammation characteristic of periodontitis." (PMID 18431474, 2008). "CXCL8 has been reported to be overexpressed in carious lesions, and a genetic variant of IL1B has been associated with caries susceptibility, and both have been reported as therapeutic targets of curcumin in periodontitis." (PMID 38920854, 2024). "Neutrophil chemotaxis in periodontitis patients has been previously reported, with pre-treatment PBNs demonstrating reduced speed, velocity and CI than healthy volunteer PBNs for the same chemoattractants (fMLP and CXCL8) employed here." (PMID 35627876, 2022). "CXCL-8 plays a significant role in the pathogenesis of periodontitis." (PMID 35187533, 2022). "Furthermore, in patients with moderate periodontitis, CXCL8 levels in GCF were statistically higher than in periodontally healthy subjects (p = 0.046)." (PMID 33726736, 2021). "Furthermore, we have found that the CXCL8 level in PISF was significantly lower than in GCF from patients with moderate periodontitis." (PMID 33726736, 2021). "The CXCL8 level in PISF was considerably lower than in patients with moderate periodontitis." (PMID 33726736, 2021). "In periodontitis, the upregulation of IL6 and CXCL8/IL8 contributes to tissue destruction and bone resorption, processes that are also regulated during orthodontic tooth movement (OTM)." (PMID 39769290, 2024). "CXCL1, CXCL3, CXCL8, CSF3, IL1A, IL1B, and IL1RN all increased in JKs in periodontitis as predicted by our atlas/DEG analyses; alternatively, SKs were relatively less active compared to JKs." (PMID 38876998, 2024). "Higher levels of CXCL1 and other chemokines were found in human and rat’s gingiva from sites of periodontitis as compared with healthy sites, and in vitro, biofilms can provoke CXCL1, CXCL3, and CXCL8 expression in epithelial cells." (PMID 37762294, 2023). "The validation analyses using RT-qPCR showed that four genes were differentially expressed in subjects with poorly controlled T2DM plus DL plus periodontitis compared to HS (TGFB1I1, VNN1, HLADRB4 and CXCL8)." (PMID 36233348, 2022). "We found that the GCF samples obtained from periodontitis patients contained significantly higher proportions of cytokines such as TNF-α, CCL2, IL-6, IFN-γ, and CXCL8 compared to the samples obtained from systemically and periodontally healthy controls." (PMID 34502071, 2021). "GCF from periodontitis patients had significantly higher concentrations of TNF-α, CCL2, IL-6, IFN-γ, and CXCL8 than controls." (PMID 34502071, 2021). "Similarly, keratinocytes in periodontitis patients show increased expression of CXCL1, CXCL3, CXCL8, CXCL13, and CCL20, suggesting that chemokine expression in gingival fibroblasts and epithelial cells drives chronic periodontitis." (PMID 40565042, 2025). "Surprisingly, epithelial cells in periodontitis patients do not show increasing levels of chemokines such as CXCL8 and other chemokines we have identified in our RNAseq assay." (PMID 37762294, 2023). "In our study, SERPINA1 was the core gene in PPI and correlated with seven ERS-related genes including ERLEC1, VWF, EDEM2, DERL3, APOE, IL6, and CXCL8, suggesting that SERPINA1 may play an essential role in the pathological process of periodontitis." (PMID 36072904, 2022).